IL6 (interleukin 6)
Diseases named in the same sentence as IL6 in open-access papers (continued):
Sharing a sentence is not in itself a finding about the gene and the disease.
depression (continued). "Pro-inflammatory cytokines such as interleukin-1 (IL-1), tumor necrosis factor alpha (TNF-α), and interleukin-6 (IL-6) have been linked to neuroinflammation in illnesses such as Alzheimer’s disease (AD), Parkinson’s disease (PD), depression, and multiple sclerosis (MS)." (PMID 39861166, 2025). "Moreover, sleep fragmentation and decreased deep sleep have been linked to increased systemic inflammation, as reflected in elevated markers such as interleukin-6 (IL-6) and C-reactive protein, which have also been implicated in the etiology of depression." (PMID 41294789, 2025). "MR analyses also indicated a potentially causal role for IL-6 signaling in depression." (PMID 41373439, 2025). "Elevated CSF quinolinic acid was found following suicide attempts with lower kynurenic acid and higher IL-6 correlating with severity of suicidality and depression, suggesting underlying pro-inflammatory cytokine activation of indoleamine 2,3-dioxygenase and the kynurenine pathway." (PMID 39994424, 2025). "Evidence from both adult and pediatric populations suggests that depression is linked to alterations in immune function, particularly involving pro-inflammatory cytokines such as interleukin-6 (IL-6), interleukin-1β (IL-1β), tumor necrosis factor-alpha (TNF-α), and interferon-gamma (IFN-γ)." (PMID 40563330, 2025). "IL-6 levels, social support, and strain may interact through shared underlying mechanisms in conferring depression risk." (PMID 41210298, 2025). "Patients with significant depression consistently show elevations in immune markers linked with chronic inflammation, such as tumor necrosis factor, interleukin (IL)-1 beta, and interleukin-6 (IL-6), as well as acute phase proteins like C-reactive protein (CRP)." (PMID 40787495, 2025). "IL-6 may cause alterations in the central nervous system and contribute to the development and severity of depression." (PMID 41274868, 2025). "Positive associations have been found between IL-6, IL-1 and the severity of depression." (PMID 39757257, 2025). "Similarly, for subjects with average levels of IL-6 at post-treatment, every 10% increase in IL-6 at T2 was associated with a 1.1% decrease in severity of cognitive symptoms of depression (b = −.112, t = -2.720, p = .013)." (PMID 39834556, 2025). "However, it is known that in the general population and in PLWH, markers of inflammation or immune activation (such as TNFα, CRP, IL-6) are closely associated to both depression and sleep quality." (PMID 40313235, 2025). "The vegetable-based dietary pattern, rich in antioxidants, fiber, and polyphenols, has been associated with lower levels of systemic inflammation, as indicated by biomarkers such as C-reactive protein and interleukin 6, both of which are implicated in depression and age-related physical decline." (PMID 41450553, 2025). "This permitted the investigation of identifying the ages where increased IL-6 associated with worse depression trajectories and whether these effects were persistent across different stages of the life course." (PMID 39865800, 2025). "Second, we conducted genetic risk score (GRS) and MR analysis to test whether genetic variants regulating levels and activity of CRP, IL-6, and GlycA were causally related with depression/cognitive performance." (PMID 38699368, 2024). "In addition, cognitive dysfunction and depression are associated with high levels of IL-6 as a pro-inflammatory cytokine." (PMID 38463908, 2024). "In our previous study, we found a significant association between the functional polymorphism of CLDN5 and stress-associated depression only when taking into account the influencing properties of the widely studied polymorphism (rs1800795) of the interleukin-6 proinflammatory cytokine." (PMID 39457114, 2024). "We hypothesised that this novel measure of IL-6 activity/bioavailability would be associated with clinical and cognitive measures previously reported to be associated with inflammation in depression." (PMID 38442505, 2024).
depression (continued). "Prolonged high levels of IL-6 have also been linked to the development of depression." (PMID 38681644, 2024). "In this study, we investigated the relationship between plasma cytokine levels and suicide risk stratification in adolescents with depression, and found high levels of IL-6, TNFα, IFN-γ, and IL-10 in the high-suicide-risk group, which is consistent with the results of previous studies." (PMID 39882160, 2024). "According to its biological function, dysregulation of IL-6 is implicated in various cognitive dysfunctions, and individuals with high concentrations of circulating IL-6 are at higher risk to develop global cognitive decline, schizophrenia, major depression, and bipolar disorder." (PMID 38605125, 2024). "Some evidence suggests that the association between CRP and depression could be confounded by other cytokines, such as IL-6." (PMID 38699297, 2024). "Mendelian Randomization (MR) analyses suggest that IL-6 may play a causal role in depression and somatic symptoms like fatigue." (PMID 38442505, 2024). "Furthermore, the research discovered that among women with a baseline diagnosis, increased IL-6 levels over time were linked to a chronic course of depression." (PMID 39273641, 2024). "Genetic risk scores (GRS) were calculated to determine whether GRS for inflammatory markers (CRP, IL-6, IL-6R, sIL-6R, GlycA) were associated with depression/anxiety, affect and cognitive outcomes." (PMID 39149475, 2024). "Therefore, the prolonged oxidative stress led to increased PDE4 which in turn decreased CERB, PRKACA and BDNF and increased IL-6, enhancing neuronal susceptibility to injury and development of depression." (PMID 38315652, 2024). "We hypothesized that both circulating CRP levels and genetically predicted inflammatory biomarkers (i.e., CRP, IL-6, sIL-6R, and GlycA) would be associated with depression, cognitive task performance, affect, and anxiety." (PMID 38699368, 2024). "IL-6 is associated and mostly elevated in patients with depression and anxiety." (PMID 37346903, 2023). "However, our analysis using the IHPP dataset was unable to confirm the association of depression with IL-6 and daily soluble fiber intake, making the mediator analysis unfeasible." (PMID 37764129, 2023). "Multiple studies have suggested that TNF-α and IL-6 levels are increased remarkably in the peripheral blood of depressed patients than in healthy controls, suggesting a strong association between inflammatory cytokines and depression." (PMID 37881439, 2023). "One of the key neuroimmune factors is interleukin (IL)-6, which is upregulated in central nervous system disorders and has been implicated in conditions, such as schizophrenia, autism, depression, Parkinson’s disease, and Alzheimer’s disease." (PMID 38260009, 2023). "Therefore, more careful studies need to be done to determine the role of TNF and IL6 in endometriosis-associated central sensitization, anxiety, and depression." (PMID 36879305, 2023). "Under this stress, the increased serum IL-6 level might be associated with the central serotonin pathway, resulting in depression symptoms." (PMID 37324195, 2023). "First, we did not collect other pro-inflammatory biomarkers, like interleukin-6 (IL-6), which might be longitudinally associated with future depression status." (PMID 36860788, 2023). "Furthermore, a European teenage survey found that long-term inactivity among individuals was associated with an increase in inflammatory markers such as IL-6, which correlate with anxiety and depression." (PMID 37763642, 2023). "In addition, a small prospective association between depression and IL-6 was observed in both directions." (PMID 36899845, 2023). "Furthermore, a meta-analysis of 22 studies concluded that depression in children and adolescents is associated with increased inflammatory factors such as IL-6 and CRP." (PMID 37840796, 2023). "Inflammatory cytokine IL-6 is also reported to be associated with depression." (PMID 36805537, 2023).
depression (continued). "All these evidence suggest for future studies to address if restoration of IL-6 level could be the key to treatment of depression associated with inflammation in GDM." (PMID 37365247, 2023). "IL-6 has also been seen to be affected in major depressive disorders, that may have caused bias in the result." (PMID 36730263, 2023). "Additionally, no statistically significant coefficient was observed regarding the association of depression with IL-6 and daily soluble fiber intake." (PMID 37764129, 2023). "Additionally, prior studies rarely incorporated blood inflammatory markers, such as IL-6 or SCFAs, when analyzing the association between gut microbiota and depression." (PMID 37764129, 2023). "The dysregulated IL-6 production is associated with cognitive and memory dysfunction, neuroinflammation, and deposition of the precursor of β-amyloid protein and is associated with schizophrenia, major depression, bipolar disorders, AD, and others." (PMID 37571401, 2023). "The levels of tumor necrosis factor-alpha (TNF-a) interleukin-1 beta (IL-1b), and interleukin 6 (IL-6) were found to be associated with depression severity as measured by BDI II, while levels of Interleukin-2 (IL-2) were found to be correlated with anxiety measured by STAI-state." (PMID 37250694, 2023). "In mice, Cldn5 ablation enhanced BBB permeability and allowed infiltration of large proteins up to ∼69 kDa (e.g., IL-6) into mouse brain parenchyma and was associated with depressive-like behavior and behavioral impairments characteristic of schizophrenia and depression." (PMID 36549907, 2023). "TL shortening is associated with increased IL-6 levels in the elderly, and we speculate that IL-6 may be a cytokine involved in depression from the early stages to advanced depression." (PMID 36805537, 2023). "And using tDCS for patients with depression with type I or II bipolar disorder, not only was the patient’s higher baseline IL-6 concentration associated with therapeutic efficacy, but the patient’s plasma IL-8 concentration also decreased significantly after treatment." (PMID 36624089, 2023). "Also, a significant association was seen between increased levels of IL-6 and the prevalence of depression (p < 0.001) and anxiety (p < 0.049)." (PMID 37621784, 2023). "The increased prevalence of depression in RA patients may be partially explained by the involvement of several immunological changes linked to RA such as upregulation of IL-6 and TNF-α are in depressive illness." (PMID 38299049, 2023). "Activation of proinflammatory cytokines, such as IL-1 and IL-6, has a certain association with the development of depression, so the impact of probiotics on immune homeostasis could help in the prevention or treatment of depression." (PMID 36839844, 2023). "Our findings therefore suggest that IL-6 may play a role in mediating the risk for depression in people living with HIV." (PMID 37280232, 2023). "Moreover, TNF and IL6 in the brain are also implicated in depression and anxiety-like behavior in mice." (PMID 36879305, 2023). "Furthermore, clustering of cancer pain and depression suggested a common underlying etiology resulted from inflammatory cytokines, such as elevated interleukin-6." (PMID 37016385, 2023). "Studies have found that IL-6 concentrations are closely associated with depression and that the pro-inflammatory factor IL-6 may be involved in the brain inflammatory response through multiple pathways." (PMID 37492068, 2023). "Additionally, a large body of literature suggests that IL‐6 plays an important role in the pathophysiology of depression, where both in clinical and pre‐clinical studies, increased IL‐6 levels are associated with a depressive phenotype." (PMID 37407501, 2023). "Elevated levels of TNF-α and IL-6 in the cerebrospinal fluid and brain parenchyma of patients with depression may be associated with enhanced microglial activity and decreased levels of astrocyte and oligodendrocyte markers." (PMID 37840923, 2023).
depression (continued). "However, only IL-6 levels showed a positive association with suicidal ideation severity longitudinally, specifically amongst those veterans at risk with current depression and history of suicide attempt with elevated suicidal ideation at study entry." (PMID 37779624, 2023). "The association between IL-6 and depression has been observed repeatedly with varying strengths." (PMID 37280232, 2023). "There are shared inflammatory mechanisms implicated in both depression and cancer such as the increasing IL‐6 and TNF‐α levels, furthermore, treatments for cancer can promote cancer‐related pain and further inflammation by enhancing cytokine production by noncancerous cells." (PMID 37991167, 2023). "Furthermore, high blood CRP and IL6 levels have been associated with greater depression symptom severity, obsessive compulsive disorder (OCD) anxiety and psychological distress." (PMID 38275640, 2023). "Authors have suggested that high IL-6 plasmatic levels are associated with faster tumor progression, reduced response to chemotherapy and decreased survival, along with a direct relationship between high stress status, depression, and abnormal social behavior." (PMID 36787313, 2023). "Increased peripheral or central IL-6 levels are associated with depression." (PMID 37371449, 2023). "Previous studies have associated IL-6 with other mental disorders, particularly with depression." (PMID 36429454, 2022). "Furthermore, TNF-α, IL-1β, and IL-17 were positively associated with HADS-D score, while high IL-1β, IL-6, and IL-17 correlated with depression occurrence." (PMID 35239774, 2022). "The occurrence of depression in SLE patients may be predicted by decreased BDNF levels and the elevated levels of autoinflammatory factors (including IL-2 and IL-6) linked to depression, as well as their interaction with gut microbiome." (PMID 36506019, 2022). "IL-6 derived from activated microglia has been implicated in depression-like behaviour." (PMID 35251047, 2022). "Depression was negatively associated with IL-6 levels (β=-0.38, p<0.05)." (PMID 36158450, 2022). "Evidence from a longitudinal twin-study suggests that different inflammatory cytokines might interact with depression differently: elevations in CRP may perhaps be a consequence of depression, while elevations in IL-6 act as a risk factor for depression." (PMID 35618889, 2022). "Besides, depression relates to the disorder of immune system, and the expression of inflammation markers (IL-6, C-reactive protein, TNF-α) increases the risk of DN." (PMID 36538528, 2022). "This herbal product was proven to prevent drug-induced pulmonary fibrosis in a mice model by decreasing the plasma levels of inflammatory cytokines, like TNF-α, interleukin citation(IL)-1, and IL-6; these mediators have been implicated in the development of depression." (PMID 36059752, 2022). "• Depression is associated with higher concentrations of IL-6, IL-10, TNF-α, and VEGF." (PMID 35836664, 2022). "Interestingly, depression symptoms were inversely associated with IL-6, after controlling for age, gender, and war exposure." (PMID 36158450, 2022). "IL-6 is also strongly and consistently associated with depression and anxiety." (PMID 35098831, 2022). "In particular, elderly patients with major depressive disorder have been associated with cognitive decline that may be related to the peripheral IL-6 level." (PMID 35887634, 2022). "Moreover, patients with RA are at increased risk of developing depression, particularly if their disease activity scores and serum IL-6 levels are increased." (PMID 35330475, 2022). "A stable negative link between depression and cognition was found in females only; a stable positive association between biomarker interleukin-6 and depression was found in females only; and a stable positive association between biomarker interleukin-8 and alcohol was found in females only." (PMID 35895279, 2022).
depression (continued). "In addition depression-mediated neuroinflammation is associated with IL-6, and there is also a positive relationship between this interleukin and the construction of TME in BC." (PMID 36364213, 2022). "These patients underwent to a massive psychological stress, which increased pro-inflammatory markers, in particular protein C and IL-6, contributing to the increase of neuroinflammation, and therefore, increasing symptoms of depression associated with sleep disorders, especially insomnia." (PMID 35994441, 2022). "IL-6 gene polymorphism is linked to a lower risk of depression with interferon therapy." (PMID 36237772, 2022). "For example, having a homozygous rare allele of the −511 ​C ​> ​T SNP of interleukin-1 beta (IL-1β) was associated with higher depression risk, while having that of the rs1800795 and rs2069840 of interleukin 6 (IL-6) could confer higher depression severity." (PMID 35528795, 2022). "Our study supports potential bidirectional causal associations between lifetime smoking and depression which may be at least in part explained by the IL-6 signalling pathway." (PMID 36057695, 2022). "Genetic variants of IL6 were linked to depression, somatization and anxiety in numerous studies." (PMID 35964023, 2022). "However, inconsistencies continue, as in a study on geriatric depression (patients 70–84 years of age), higher levels of IL-8 and IL-6 in CSF were associated with current depression." (PMID 36614020, 2022). "Other authors suggested that higher levels of IL-6 are linked to both fatigue and pain and that this connection may contribute to the occurrence of depression." (PMID 35330475, 2022). "However, evidence for increased IL6 gene expression is consistent with reports of elevated interleukin-6 (IL-6) being associated with dissociative symptoms in depression and with elevated levels of IL-6 in other trauma spectrum disorders." (PMID 35627228, 2022). "Inflammatory biomarkers (IL-6 and IL-2) have been linked to depression." (PMID 36506019, 2022). "At present, the etiology and pathogenesis of depression are still remained unclear; although abnormal immune dysfunction and autoimmunity has been suspected as one of the reason, the association between IL-6 and IL-17 and the etiology as well as pathogenesis of depressive disorder is unclear." (PMID 35615531, 2022). "First, it was reported that depression is associated with a chronic low-grade inflammatory response, and depressed patients have elevated levels of inflammatory cytokines such as interleukin-2 and interleukin-6, which are associated with decreased BMD." (PMID 36348273, 2022). "In addition, inflammatory factors impair neuronal synaptic plasticity and thus cause abnormal neuronal function, e.g., IL-6 reduces neuronal synaptic plasticity and accelerates depression." (PMID 36440427, 2022). "Elevated IL-6 levels have previously also been linked to depression in older adults and recent studies also found increases in Glx in the anterior or posterior cingulate cortex with LCModel in adolescents with suicidal ideation or in cognitively impaired adults." (PMID 35479493, 2022). "Nevertheless, the underlying mechanisms of IL-6 function and associations with other possible involved factors in depression are still unknown." (PMID 36368945, 2022). "Our study showed a correlation of IL-6 and elevated stress levels, which emphasize the findings of other authors, that higher levels of IL-6 are associated with mental health problems such as depression and anxiety." (PMID 36064560, 2022). "Similarly, in a study of older adults, depression six years earlier was associated with levels of interleukin-6 (IL-6) and (marginally) CRP." (PMID 35617264, 2022). "The mother's level of interleukin 6 may rise after a cesarean section, and since interleukin 6 is a key cytokine alteration associated with depression, it is the mediating mechanism between the two." (PMID 36465774, 2022).